LCE1C (late cornified envelope 1C)
Description:
Precursors of the cornified envelope of the stratum corneum.
Synonyms: LEP3
Tractability: No criterion of Open Targets' tractability assessment is met for any kind of drug.
Gene: Protein-coding gene on chromosome 1 (152,804,832 to 152,806,651, reverse strand). Ensembl gene ENSG00000197084.
Pathways (Reactome):
Developmental Biology: Formation of the cornified envelope
Gene Ontology:
Molecular function: protein binding
Biological process: epidermis development
Genetic constraint (gnomAD): Loss-of-function variants: 7 observed, 4.75 expected, observed/expected ratio (o/e) 1.47, 90% interval 0.78 to 1.93. That is too few expected variants to judge how well the gene tolerates losing a copy. Missense variants: 136 observed, 148.66 expected, observed/expected ratio (o/e) 0.91, 90% interval 0.8 to 1.05. Synonymous variants: 72 observed, 56.89 expected, observed/expected ratio (o/e) 1.27, 90% interval 1.04 to 1.54.
Homologues: Orthologues: chimpanzee LCE1C (100% identical). Paralogues in human: LCE1B (97% identical).
Diseases named in the same sentence as LCE1C in open-access papers:
LCE1C is named in the same sentence as 4 diseases in open-access papers, as found by Europe PMC text mining. Sharing a sentence is not in itself a finding about the gene and the disease. The quoted sentences say what the papers report.
sarcopenia (1 paper, 2023). Progressive decline in muscle mass due to aging which results in decreased functional capacity of muscles. "In contrast, SLURP1 and LCE1C expression levels were much higher in sarcopenia patients and associated with a worse prognosis and weaker immune profile." (PMID 37138756, 2023). "In addition, we analyzed the association of various immune signatures with the pre-defined top-ranked genes (TTC39DP, SLURP1, and LCE1C) that discriminated sarcopenia from healthy individuals." (PMID 37138756, 2023). "Among deferentially expressed genes (DEGs) and the elastic net regression model, we found five common genes (TTC39DP, SLURP1, LCE1C, PTCD2P1, and OR7E109P) that discriminated between sarcopenia patients and healthy controls with a different range." (PMID 37138756, 2023).
LCE1C also shares sentences with these, for which no sentence is quoted: cancer (1 paper); childhood onset asthma (1); Parkinson disease (1).